NRXN3 (neurexin 3)
Diseases named in the same sentence as NRXN3 in open-access papers (continued):
Sharing a sentence is not in itself a finding about the gene and the disease.
glioma (9 papers, 2013 to 2025). A benign or malignant brain and spinal cord tumor that arises from glial cells (astrocytes, oligodendrocytes, ependymal cells). "FoxQ1 seemed to crucially regulate NRXN3 expression through direct interaction with NRXN3 promoter, as mutation of FoxQ1 binding sites significantly up-regulated NRXN3 promoter activity in glioma cells." (PMID 23383267, 2013). "NRXN3 functions in the vertebrate nervous system as cell adhesion molecules and receptors and was previously found to be mutated in colon cancer, breast cancer, glioma, squamous cell carcinoma of the head and neck and ovary cancer." (PMID 23301059, 2013). "NRXN3 belongs to a family of highly polymorphic neuronal‐specific cell surface proteins, and it was reported to promote glioma cell proliferation and migration under the regulation of Fox Q1." (PMID 35429411, 2022). "The expression level of these candidate genes in a public database (GEPIA) was searched, and only two of them (serine rich and transmembrane domain containing 1 (SERTM1), and NRXN3) were downregulated in gliomas." (PMID 34035217, 2021). "Overall, these findings suggested that miR-431 can regulate the proliferation, migration and invasion of glioma cells by targeting NRXN3." (PMID 34035217, 2021). "Western blot analysis and IHC showed that cyclin D1, cyclin D2, CDK4, CDK6, Ki-67, Bcl-2 and Bax were involved in the NRXN3-induced inhibitory effect on glioma growth." (PMID 34035217, 2021). "The current study found that NRXN3 was downregulated in gliomas and inhibited the proliferation, migration and invasion of glioma cells." (PMID 34035217, 2021). "Inhibition of FoxQ1 in glioma cells by transfection of FoxQ1 shRNA significantly up-regulated NRXN3 expression and reduced the ability of proliferation and migration in glioma cells, whereas overexpression of a FoxQ1 expression vector did the opposite." (PMID 23383267, 2013). "Next, we tested the function of FoxQ1/NRXN3 interaction by assessing their roles in glioma cells biological behaviors." (PMID 23383267, 2013). "We sought to determine the molecular mechanism by which FoxQ1 promote glioma development by down-regulating NRXN3 expression." (PMID 23383267, 2013). "To determine the FoxQ1 and NRXN3 expression levels in glioma cells lines and normal human astrocytes cells, we examined the FoxQ1 and NRXN3 expression in Hs683, U-87MG, SW1088, LN-229 and NHA cells by RT-qPCR and Western blot." (PMID 23383267, 2013). "In the present study, we showed that FoxQ1 expression was higher in glioma specimens than the normal tissues, whereas NRXN3 expression was lower in glioma specimens." (PMID 23383267, 2013). "Of more importance, we found that FoxQ1 directly regulated NRXN3 expression and glioma proliferation and migration." (PMID 23383267, 2013). "Together, our results indicated that FoxQ1 enhances the ability of glioma cells proliferation and migration by down-regulation of NRXN3 expression in vitro." (PMID 23383267, 2013). "The relation between FoxQ1/NRXN3 expression and survival of patients with gliomas need to be clarified in future study." (PMID 23383267, 2013). "Reverse transcription quantitative real-time PCR (RT-qPCR) and Western blot were used to determine the FoxQ1 and Neurexins 3 (NRXN3) expression in gliomas." (PMID 23383267, 2013). "FoxQ1 mRNA and protein were up-regulated in gliomas and negatively related to the NRXN3 expression (r = −0.373, P = 0.042)." (PMID 23383267, 2013). "To provide direct evidence that FoxQ1 affect the malignant phenotype by down-regulation of NRXN3 in glioma cells, we transfected NRXN3 shRNA into FoxQ1-shRNA2 to rescue the NRXN3 expression and established the stable clone (NRXN3-rescue)." (PMID 23383267, 2013). "In conclusion, we have shown that FoxQ1 was highly expressed, whereas NRXN3 was lowly expressed in gliomas." (PMID 23383267, 2013).
glioma (continued). "Similarly, FOXQ1 is highly expressed and directly regulates the inhibition of neurexins 3 (NRXN3) expression, thereby promoting to proliferation and migration in glioma cells." (PMID 41347087, 2025). "The expression pattern of NRXN3 in clinical glioma specimens was investigated, which showed that NRXN3 was downregulated in glioma tissue and associated with WHO malignancy grades of gliomas." (PMID 34035217, 2021). "In conclusion, the current study demonstrated that circ_0001367 was downregulated in gliomas and could inhibit glioma progression by sponging miR-431 to regulate NRXN3." (PMID 34035217, 2021). "The expression level of NRXN3 in glioma cell lines was consistent with that in clinical specimens." (PMID 34035217, 2021). "Functional assays indicated that miR-431 mimics and sh-NRXN3 promoted the proliferation, migration and invasion of glioma cells and that the promoting effect of miR-431 mimics could be restored by NRXN3 overexpression." (PMID 34035217, 2021). "In conclusion, circ_0001367 functions as an suppressor in glioma by targeting the miR-431/NRXN3 axis and may be a promising therapeutic target against gliomas." (PMID 34035217, 2021). "Finally, the FoxQ1 expression levels directly affected the glioma cells proliferation and migration in a NRXN3-dependent manner both in vitro and in vivo." (PMID 23383267, 2013). "Thus, our work indicated that FoxQ1 regulates gliomas development by down-regulation of NRXN3 expression." (PMID 23383267, 2013). "Therefore, our results suggest that NRXN3 expression negatively related to FoxQ1 expression in human glioma tissues." (PMID 23383267, 2013). "Furthermore, we first identified NRXN3 was down-regulation in the glioma specimens, which suggested that NRXN3 is a potential tumor suppressor." (PMID 23383267, 2013). "FoxQ1 promotes glioma cell proliferation and migration by down-regulation of NRXN3 expression." (PMID 23383267, 2013). "FoxQ1 expression negatively related to the NRXN3 expression in glioma specimens." (PMID 23383267, 2013). "Therefore, FoxQ1 overexpression contributes directly to NRXN3 underexpression in gliomas and seems to be critical for glioma development." (PMID 23383267, 2013). "Furthermore, we performed transwell assay to assess the function role of FoxQ1/NRXN3 in glioma cells migration." (PMID 23383267, 2013). "Similarly, NRXN3 (Neurexin 3) was involved neuron cell-cell adhesion and glioma cell migration." (PMID 27100869, 2016). "Furthermore, FoxQ1 expression negatively related to NRXN3 expression in human glioma tissues." (PMID 23383267, 2013). "Other possible consequences of the activity of circRNAs are the downregulation of apoptotic effectors such as caspase 3 or the upregulation of tumor suppressors such as the presynaptic adhesion molecule neurexin 3 (NRXN3), which inhibits glioma growth in vivo." (PMID 37626776, 2023). "Thus, we hypothesized that FoxQ1 promotes glioma development by downregulation of NRXN3 expression." (PMID 23383267, 2013).
nicotine dependence (5 papers, 2010 to 2022). Physical and psychological dependence on nicotine. "A study showed that the NRXN3 gene is a potential factor affecting the risk of nicotine addiction and that the NRXN3 marker rs1004212 is significantly related to the amount of smoking." (PMID 35309141, 2022). "The gene for one of the neurexin family proteins, neurexin-3, is associated with nicotine dependence, opioid dependence, and poly-substance abuse, and cocaine exposure increases neurexin-3 expression in the globus pallidus of mice." (PMID 20617039, 2010). "NRXN3 and GABBR2 were identified using this approach and also in linkage studies of opiate dependence and association studies of nicotine dependence, for example." (PMID 20098672, 2010). "NRXN3, a member of the neurexins gene family, has been shown to be related to nicotine dependence." (PMID 34417442, 2021).
alcohol dependence (4 papers, 2010 to 2022). Physical and psychological dependence on alcohol. "Data from postmortem human cerebral cortical brain samples showed that NRXN3 polymorphisms are associated with alcohol dependence and the altered expression of specific isoform." (PMID 24265751, 2013). "Therefore, this polymorphism might increase the risk of alcoholism by affecting the alternative splicing of exon 23 and modulating the synaptic function of neurexin-3." (PMID 20617039, 2010).
breast carcinoma (4 papers, 2013 to 2024). "Emerging research suggests a role of NRXN3 in cancer progression, including breast cancer, through its involvement in cellular adhesion, migration, and invasion." (PMID 38217262, 2024).
developmental delay (3 papers, 2023 to 2024). "Most recently, a case study of a young girl with ASD and global developmental delay reported a ß-specific frameshift mutation 15 amino acids downstream of the signal peptide in exon 18 of Nrxn3." (PMID 38279285, 2024).
nasopharyngeal carcinoma (3 papers, 2021 to 2024). A carcinoma arising from the nasopharyngeal epithelium. "Interestingly, hypermethylation of ZNF582, the same class as zinc finger protein associated with L-leucine in our research, regulated the transcription of NRXN3 in nasopharyngeal carcinoma." (PMID 38049855, 2023).
opioid dependence (3 papers, 2010 to 2013). "The genome-wide linkage study of opioid dependence located a region on chromosome 14q; the peak encompasses the NRXN3 gene." (PMID 24265751, 2013).
Borderline personality disorder (2 papers, 2013 to 2021). A personality disorder characterized by impulsive behavior and unpredictable, capricious mood. "And finally, an association study on Australian borderline personality disorder (BPD) patients showed that several NRXN3 SNPS were nominally associated with BPD in heroin-dependent cases." (PMID 34610269, 2021). "A recent study observed an association between NRXN3 polymorphisms and borderline personality disorder phenotypes in heroin-dependent cases." (PMID 24265751, 2013).
central obesity (2 papers, 2011 to 2018). "The aim of the present study was to investigate central obesity-associated variants in LYPLAL1, NRXN3, MSRA, and TFAP2B for associations with quantitative metabolic traits in a population-based sample of 6,038 adult Danes (The Inter99 study sample)." (PMID 21674055, 2011). "In conclusion, we found that several of the central obesity-associated variants in LYPLAL1, NRXN3, MSRA, and TFAP2B associated with metabolic and anthropometric traits among adult Danes." (PMID 21674055, 2011). "In this study we found several associations with quantitative metabolic and anthropometric traits for the central obesity-associated variants in LYPLAL1, NRXN3, MSRA, and TFAP2B." (PMID 21674055, 2011). "We demonstrate that several of the central obesity-associated variants in LYPLAL1, NRXN3, MSRA, and TFAP2B associate with metabolic and anthropometric traits in Danish adults." (PMID 21674055, 2011).
Cognitive impairment (2 papers, 2022 to 2023). Abnormal cognition is characterized by deficits in thinking, reasoning, or remembering. "Our data thus indicate that binding of presynaptic Nrxn3α to postsynaptic dystroglycan enables a normal presynaptic release probability at inhibitory synapses, which may explain -at least in part- why mutations in Nrxn3 and in dystroglycan-associated proteins induce cognitive impairments." (PMID 36997523, 2023).
dementia (2 papers, 2022 to 2024). Loss of intellectual abilities interfering with an individual's social and occupational functions. "Survival analyses from CSF proteomics from the Knight ADRC identified several synaptic genes associated with an increased risk of dementia, such as IGF1, NRXN3, and YWHAZ." (PMID 38687811, 2024). "Our results showed that 11 of 13 (84%) proteins encoded by synaptic genes including IGF1, NRXN3, and YWHAZ were associated with an increased risk of dementia progression." (PMID 38687811, 2024).
dependence (2 papers, 2010 to 2018). "However, further research is needed in both humans and animal models to solidify this potential role of NRXN3, and NRXN3 genetic variance, in drug dependence." (PMID 29675039, 2018).
encephalitis (2 papers, 2021 to 2022). An acute inflammatory process affecting the brain parenchyma. "Several novel antibodies associated with encephalitis have been reported in the last 5 years, such as synapsin and neurexin 3 alpha antibodies." (PMID 33026492, 2021). "ELISA, enzyme‐linked immunosorbent assay; NFASC, neurofascin; NLGN2, neuroligin 2; NRXN3, neurexin 3; VE, viral encephalitis." (PMID 37786892, 2022). "Thus, it is not surprising that confusion and disorientation were observed as prominent symptoms in patients diagnosed with synapsin and neurexin 3 alpha encephalitis." (PMID 33026492, 2021).
type 2 diabetes (2 papers, 2015 to 2018). "If NRXN3 is confirmed to be important in PDR, there may be overlapping genetic risk factors for risk of type 2 diabetes and PDR." (PMID 29739359, 2018).
adenoma (1 paper, 2013). A neoplasm arising from the epithelium. "We found that CDH20 and LAMA3 were mutated in the adenoma while NRXN3 and COL4A6 were mutated in the adenocarcinoma." (PMID 23301059, 2013). "CDH20 and LAMA3 were mutated in the adenoma while NRXN3 and COL4A6 were mutated in the adenocarcinoma from the same patient, suggesting for the first time that genetic alterations in the cell adhesion pathway occur as early as in the adenoma." (PMID 23301059, 2013).
age-related macular degeneration (1 paper, 2018). Age-related loss of vision in the central portion of the retina (macula), secondary to retinal degeneration. "NRXN3 polymorphisms are also associated with smoking behaviour, which in turn is a risk factor for age-related macular degeneration although the contributory role of smoking to DR is less than for age-related macular degeneration." (PMID 29739359, 2018).
alcohol addictions (1 paper, 2020). "Human genomic studies of neurexin 3 (NRXN3) have shown disruption of brain structure, function, and subsequent behavior with nicotine, opioid, and alcohol addictions through the alteration of expression of NRXN3 isoforms." (PMID 31991879, 2020).
Anxiety (1 paper, 2024). Intense feelings of nervousness, tension, or panic often arise in response to interpersonal stresses. "Four genes were associated with both treatment outcomes and these symptom dimensions: CGREF1 (anxiety); MCHR1 (neuroticism); FTO and NRXN3 (sleep)." (PMID 39191930, 2024).
cervix cancer (1 paper, 2021). "NXPH1 and its two downstream receptors, NRXN1 and NRXN3, have established 1722 cell-to-cell communications, accounting for 97.6% of all possible cell-cell links in cervix cancer cell lines." (PMID 35052689, 2021).
Cluster headache (1 paper, 2022). A type of headache characterized by repeated attacks of unilateral pain lasting 15 to 180 minutes and associated with local autonomic signs. "A small number of studies have also suggested that NRXN3 rearrangement may be related to cluster headaches in some cases." (PMID 37786892, 2022).
colon adenoma (1 paper, 2013). An adenoma that arises from the colon. "Among these mutated genes, mutations in APC, FBXW7, KIAA1409, COL4A6, FAM181A, TFR2 and NRXN3 were previously reported in colon adenomas or adenocarcinomas." (PMID 23301059, 2013).
colon cancers (1 paper, 2013). "In addition, 5 other mutated genes were previously reported in colon cancers including FAM181A, NRXN3, KIAA1409, TFR2, and COL4A6." (PMID 23301059, 2013).
eating disorder (1 paper, 2011). A broad group of psychological disorders with abnormal eating behaviors leading to physiological effects from overeating or insufficient food intake. "Eating disorders have been ascribed to the hypothalamic part of the brain, and recently, NRXN3 has been investigated in relation to addiction of alcohol and smoking." (PMID 21674055, 2011).
fragile X syndrome (1 paper, 2017). A genetic syndrome caused by mutations in the FMR1 gene which is responsible for the expression of the fragile X mental retardation 1 protein. "For this analysis, one subject with Fragile X syndrome was excluded but three subjects with clinically significant CNVs (A2BP1/RBFOX1 deletion (1.0 < WB5HT-z < 1.75), maternal interstitial duplication 15q11-q13 (Normal-5HT group), and NRXN3 deletion (Normal-5HT group)) were included." (PMID 28344757, 2017).
glioblastoma (1 paper, 2013). The most malignant astrocytic tumor (WHO grade IV). "Our RT-qPCR analyses showed a significant association between FoxQ1 overexpression and decreased NRXN3 expression in 30 matched primary glioblastoma tissues and the adjacent normal brain tissues and Western blot further confirmed the correlation in 6 matched specimens." (PMID 23383267, 2013). "Our results indicate that suppression of FoxQ1 expression increase NRXN3 expression in glioblastoma cells." (PMID 23383267, 2013). "Our results indicate that inhibition of FoxQ1 expression significantly suppresses the tumorigenicity of human glioblastoma cells, whereas rescue the NRXN3 expression can recover the ability of tumorigenicity." (PMID 23383267, 2013). "We first determined the FoxQ1 and NRXN3 mRNA expression in 30 human glioblastoma and the paired adjacent normal brain specimens by RT-qPCR analyses." (PMID 23383267, 2013).
heart failure (1 paper, 2024). Inability of the heart to pump blood at an adequate rate to meet tissue metabolic requirements. "Kaplan–Meier curves illustrate a higher incidence of heart failure in the lowest quartile of ERRB3 and highest quartile of HSPA2; there were no interquartile differences for NRXN3." (PMID 39180332, 2024).
Huntington disease (1 paper, 2023). Huntington disease (HD) is a rare neurodegenerative disorder of the central nervous system characterized by unwanted choreatic movements, behavioral and psychiatric disturbances and dementia. "In addition, the changes in the protein NRXN3 level in the brain cerebrospinal fluid derived from Huntington’s disease agreed with the protein and mRNA levels of ZNF503." (PMID 38049855, 2023).
malignant melanoma (1 paper, 2014). "The other LOH at chr14q31.1 hits gene NRXN3, which has been related to malignant melanoma." (PMID 25201439, 2014).
mental disorder (1 paper, 2013). A disease that has its basis in the disruption of mental process. "The association with DEACMP enhances NRXN3 as a susceptibility gene for mental disorders and neurological disease." (PMID 24265751, 2013).
muscular dystrophy (1 paper, 2022). Muscular dystrophy (MD) refers to a group of more than 30 genetic diseases characterized by progressive weakness and degeneration of the skeletal muscles that control movement. "NRXN3-related pathways include muscular dystrophy and protein interactions at synapses." (PMID 35309141, 2022).
pancreatic cancer (1 paper, 2023). "Particularly, the G allele of rs2370981 mapped to NRXN3, strongly related to eicosa-11,14,17-trienoic acid, was identified as a protective allele for pancreatic cancer [OR = 0.371, p = 0.043]." (PMID 38049855, 2023).
Pitt-Hopkins-like syndrome 2 (1 paper, 2017). Any Pitt-Hopkins-like syndrome in which the cause of the disease is a mutation in the NRXN1 gene. "NRXN3 encodes a member of the neurexin family of which NRXN1 is associated with Pitt-Hopkins-like syndrome 2 (MIM 614325) and ACOT1 is involved in lipid metabolism." (PMID 28327206, 2017).
preeclampsia (1 paper, 2025). Preeclampsia is a hypertensive disorder of pregnancy that is characterized by new-onset hypertension with proteinuria presenting after 20 weeks of gestation, and depending on mild or severe forms may initially present with severe headache, visual disturbances, and hyperreflexia. "Although late-onset preeclampsia is not as strongly associated with placental vascular dysfunction as early-onset preeclampsia, genes such as CP, IGFBP7, CDH13, ROBO1, UNC5C, NRXN3, and ITGA1 suggest subtle changes in angiogenic pathways." (PMID 41444673, 2025).
Skin-Melanoma (1 paper, 2025). "In Thy-AdenoCA, the genes NRXN3 and LRP1B exceeded this threshold, as well as PCDH15 in Eso-AdenoCA and Skin-Melanoma." (PMID 40507213, 2025).